PALB2 (partner and localizer of BRCA2)
Diseases named in the same sentence as PALB2 in open-access papers (continued):
Sharing a sentence is not in itself a finding about the gene and the disease.
breast cancer (continued). "The gene panels include genes with a well-documented association between a rare-monogenic variant and breast cancer (e.g., BRCA1, BRCA2 and PALB2)." (PMID 34755241, 2022). "Rare germline variants in the high-risk genes BRCA1 and BRCA2 together with the moderate-risk genes such as PALB2, ATM, CHEK2, and BRIP1 account for about 30% of breast cancer predisposition." (PMID 34755241, 2022). "Another genetic variation associated with intermediate dangers of breast cancer and a 20%–40% lifetime chance of getting breast cancer includes the CHEK2, ATM, and PALB2 genes involved in the DNA repair process." (PMID 35762299, 2022). "Hypermethylation of the promoters of tumor suppressor genes ATM, NOTCH1, NUP98, PALB2, TSC2, and WRN had all previously been associated with WTC exposure and were again observed to be hypermethylated in WTC EHC compared to NYUWHS breast cancer patients." (PMID 35564499, 2022). "For our exemplar clinical scenario, we applied this pathway to BRCA-testing (BRCA1/BRCA2/PALB2 gene testing) in unselected mainstream patients with breast cancer." (PMID 35868849, 2022). "Here we selected ten potentially pathogenic PALB2 VUSs identified in 2279 Chinese patients with breast cancer and evaluated their impacts on PALB2 function by systematic functional assays." (PMID 35853885, 2022). "More recently, the largest WES study for overall breast cancer reported increased breast cancer risk associated with ATM, CHEK2, PALB2, and MSH6." (PMID 35884425, 2022). "Targeted enrichment sequencing of the panel of 32 known or suspected breast cancer susceptibility genes confirmed the associations of known breast cancer susceptibility genes ATM, CHEK2, and PALB2." (PMID 35884425, 2022). "In all but one case, the variants were still reported because of risk for later-onset cancers, such as breast cancer in ATM and PALB2 mutation carriers." (PMID 36182817, 2022). "Recently, several studies have demonstrated benefits of PARPi treatment in breast cancer patients with germline PALB2 variants." (PMID 35853885, 2022). "In 2013, we reported that monoallelic loss of the essential autophagy gene Becn1 delays spontaneous mammary tumor formation following conditional knockout (CKO) of Palb2 in mice." (PMID 40396054, 2022). "PAM50 classification versus PALB2 gene RNA expression, 1097 breast cancer subjects, indicated that PALB2 expression was highest in Luminal B subtype subjects (p = 0.0094, one way ANOVA)." (PMID 35779338, 2022). "It is now estimated that 10–25% of breast carcinomas are associated with HRD, due to BRCA1/2 PV, but also of other genes such as PALB2, ATM, ATR, BARD1, RAD51, BRIP1, or FANC." (PMID 35158866, 2022). "Deleterious variants in DNA damage response genes, mainly in lung cancer, are associated with a higher mutational burden, as observed in breast carcinomas with DNA damage repair gene variants and in our tumor samples with BRCA1, BRCA2, and PALB2 variants." (PMID 35875117, 2022).
breast cancer (continued). "A comparison cohort of breast cancers with expected HR defects from PALB2 (n = 15) and RAD51C (n = 9) germline LoF variant carriers, and 115 sporadic breast cancers sequenced using the same platform, were also evaluated." (PMID 33980861, 2021). "PALB2 PGVs showed perfect segregation in 20/20 first-degree relatives with breast cancer, compared with 7/13 for CHEK2_1100delC (P = 0.002)." (PMID 34113003, 2021). "In summary, case-control comparisons yielded high estimates of relative risk for breast cancer, and even higher estimates for TNBC, for BRCA1, BRCA2, and PALB2 among both EA and AA women." (PMID 33479248, 2021). "Another French-Canadian woman with breast cancer was found to harbor PALB2 c.2323C>T and BRCA2 c.9004G>A." (PMID 34439348, 2021). "Twenty founder alleles in BRCA1, BRCA2, CHEK2, NBN, PALB2 and RECQL genes are responsible for the majority of hereditary breast cancers in Polish women." (PMID 34461861, 2021). "We recommend that a simple test for Polish founder mutations in BRCA1, BRCA2, PALB2 and CHEK2 should be offered to all male breast cancer patients in Poland." (PMID 34461861, 2021). "In Jamaica, we found a 5.5% (10 of 183) rate of inherited breast cancer with germline variants in BRCA1, BRCA2, PALB2, STK11, and NBN genes." (PMID 33646313, 2021). "In conclusion, we recommend that a molecular test for BRCA1, BRCA2, PALB2 and CHEK2 recurrent mutations should be offered to male breast cancer patients in Poland." (PMID 34461861, 2021). "Among these, BRCA1, BRCA2, and PALB2 were still classified as high risk, and ATM, BARD1, CHEK2, and RAD51D were still classified as moderate risk breast cancer susceptibility genes in Chinese women." (PMID 34606182, 2021). "In the present study, we show that histologically normal breast tissue from younger women who are susceptible to breast cancer, as a result of harboring a germline mutation in BRCA1, BRCA2 or PALB2 genes, exhibits hallmarks of accelerated aging." (PMID 35187501, 2021). "Four of the PALB2 carriers had multiple cancers including breast cancer, ovarian cancer, colorectal cancer, or cancer in the uterus." (PMID 34439348, 2021). "PARGi is also synthetically lethal in BRCA1, BRCA2, PALB2, FAM175A and BARD1 deficient breast cancer cells." (PMID 33674744, 2021). "Odds ratios for breast cancer and PALB2 were similar to odds ratios for breast cancer and BRCA2, and higher than odds ratios previously reported for PALB26." (PMID 33479248, 2021). "Moderate penetrance breast cancer susceptibility gene mutations such as PALB2, CHEK2, ATM occur in 4-6% of breast cancer patients." (PMID 34422626, 2021). "Human breast cancers from BRCA and PALB2 germline mutation carriers show higher mutational burden, HRD signature, and LST scores than sporadic cancers." (PMID 33893322, 2021). "Our study found a somewhat different pattern of sensitivity to drugs in PDX coming from chemotherapy-naïve TNBC patients with and without mutations in genes involved in DNA homologous recombination repair (BCRA1 and PALB2) and hereditary breast cancer." (PMID 33782404, 2021). "Pathogenic variants in the breast cancer genes of BRCA1, BRCA2, and PALB2 are common causes of breast cancer in Caribbean women." (PMID 33646313, 2021). "A grade 3 ER-positive HER2-negative phenotype occurred in 15/43 (34.9%) PALB2 PGVs, while accounting for 254/1843 (13.8%) breast cancers (OR = 3.35, 95% CI = 1.76-6.44, P = 0.0005)." (PMID 34113003, 2021).
breast cancer (continued). "Recently published guidelines offer recommendations on the management of breast cancer in patients with germline mutations in BRCA1/2, PALB2, CHEK2 and ATM." (PMID 34422626, 2021). "The mean age at diagnosis of first breast cancer for those with a PALB2 PGV was 49.8 years (median 50 years, SEM = 2.30, range = 24–77 years) and, for the CHEK2_c.1100delCPGV, 49.3 years (median 49.3 years, SEM 1.83, range 27–76 years)." (PMID 34113003, 2021). "Here, the TNT phenotype occurred in 12/43 (27.9%) PALB2 PGVs, as compared with 11.1% (204/1843) of all breast cancers cases known to our service where full histology was known (OR = 3.11, 95% CI = 1.61–5.96, P = 0.002)." (PMID 34113003, 2021). "reviewed 715 male breast cancer patients who underwent germline multi-gene panel testing and found that pathogenic variants in CHEK2 (OR = 3.7, p = 6.24 × 10-24) and PALB2 (OR = 6.6, p = 0.01) were both significantly associated with breast cancer risk in men." (PMID 33959510, 2021). "PALB2 encodes a protein that interacts with BRCA2 to execute double-stranded DNA repair through homologous recombination (HR) and was identified as a breast cancer predisposition gene in 2007." (PMID 33854214, 2021). "A founder mutation of BRCA1, BRCA2, CHEK2, PALB2 and NBN was found in 13.3% of men with breast cancer in Poland." (PMID 34461861, 2021). "Considering the breast cancer only index cases, there were 33 PALB2 PGVs and 43 CHEK2_c.1100delC PGVs (PALB2: OR = 6.16, 95% CI = 1.98–19.21, P = 0.0003; CHEK2: OR = 4.83, 95% CI = 2.01–11.34, P = 0.0001)." (PMID 34113003, 2021). "A phase II clinical trial of talazoparib was performed on patients with HER2– breast cancer or other tumors with mutated HR pathway genes, which showed a RECIST response in patients carrying PALB2 mutations." (PMID 34439348, 2021). "Overall, germline BRCA1 mutated cancers had significantly higher cyclin E1 protein than the BRCA1 wildtype cases, and tumors with other breast cancer associated germline mutations (BRCA2, PALB2, or CHEK2)." (PMID 34465787, 2021). "In 101 breast cancer patients, we have detected two mutations in CHECK2 (c.444+1G>A (n=1) and del5395 (exon 10–11 deletion) (n = 1)) and two mutations in PALB2 (c.509_510delGA (n = 1) and c.172_175delTTGT (n = 1))." (PMID 33918338, 2021).
breast cancer (continued). "Women were defined as high risk if they had a germline mutation that greatly increases lifetime risk of a breast cancer diagnosis including BRCA1, BRCA2 and PALB2 (refs.2,18)." (PMID 35187501, 2021). "The BGP population is ideal to study further the risk effects of breast cancer predisposing PVs such as BRCA1:c.190T>C and PALB2:c.1027C>T." (PMID 33573335, 2021). "Other breast cancer susceptibility genes that have equivalent information include BRCA2 (penetrance to age 70, 45% (95% CI, 31–56%), PALB2 (penetrance to age 70, 44% (95% CI, 37–52%) and BRCA1 (penetrance to age 70, 65% (95% CI, 44–78%)." (PMID 33803639, 2021). "As for FBC, pathogenic mutations in other breast cancer genes have also been recently associated with an increased risk of MBC, such as PALB2 and CHEK2 mutations." (PMID 34298749, 2021). "The PALB2 (partner and localizer of BRCA2) mutation was found to be associated with an increased risk of breast cancer and one of the most common mutations, after BRCA1 and BRCA2, in non-BRCA1/2 breast cancer patients." (PMID 34439348, 2021). "ER- breast cancer more commonly involves mutation of DNA repair genes including BRCA1/2, PALB2 and members of the Fanconi Anemia pathway, which result in STING pathway activation." (PMID 34172750, 2021). "Similar results were found through a screening of 65,057 white woman with breast cancer where a high or moderately increased risk of disease was found in relation with pathogenic mutations in ATM, CHEK2, PALB2, and RAD51D." (PMID 34299313, 2021). "In the current study, we evaluated the frequency of 20 recurrent mutations in six genes (BRCA1, BRCA2, CHEK2, PALB2, NBN and RECQL) in 165 men diagnosed with breast cancer in Poland." (PMID 34461861, 2021). "We estimated the prevalence of 20 alleles in six genes (BRCA1, BRCA2, CHEK2, PALB2, NBN, RECQL) in 165 Polish male breast cancer patients." (PMID 34461861, 2021). "Other clinical trials are evaluating the potential role of PARP inhibitors in the treatment of PALB2 PVs carriers with breast cancer." (PMID 33718150, 2021). "In humans, germline heterozygous BRCA1 mutations cause the highest risk and earliest onset of breast cancer, followed by BRCA2 and then PALB2 mutations." (PMID 33893322, 2021). "There was perfect segregation of PALB2 PGVs in all 20 first-degree relatives (FDRs) with breast cancer who were available for testing; many FDRs with breast cancer were deceased and unavailable for testing and not all living FDRs opted for testing." (PMID 34113003, 2021). "Here, we report a novel large germline deletion in PALB2 in a young breast cancer patient who had a family history for different cancer types." (PMID 33718150, 2021). "Biallelic carriers of PVs in other, dominant breast cancer susceptibility genes such as BRCA2, ATM, PALB2, and NBN are known to have more severe cancer phenotypes than monoallelic carriers." (PMID 31993860, 2020). "Other studies using multigene panels found that over 4% of women at risk of hereditary breast cancer had mutations in genes other than BRCA1/2, including PALB2, CHEK2, and ATM." (PMID 32090079, 2020). "Genetic testing of PALB2 has been suggested for clinical testing in breast cancer families and in specific subgroups of medulloblastoma based on clinical and molecular tumor characteristics." (PMID 32056145, 2020). "The germline mutation rate of the members of the Fanconi anemia gene family (including BRCA2, PALB2, and RAD51C) was 25.93% (7/27) among patients with germline mutations in TNBC, which was lower than those in unselected breast cancer." (PMID 33194720, 2020).
breast cancer (continued). "There are twenty recurrent mutations in six breast-cancer-predisposing genes in Poland (BRCA1, BRCA2, CHEK2, PALB2, NBN, and RECQL)." (PMID 32824581, 2020). "The goal of the current study was to estimate the prevalence of twenty alleles in six genes, BRCA1/2, CHEK2, PALB2, NBN, and RECQL, in Polish early-onset breast cancer patients." (PMID 32824581, 2020). "We also refer to both the opportunities and challenges that the identification of PALB2 PVs provides in breast cancer genetic counseling and precision medicine." (PMID 32185139, 2020). "These PALB2-HET HBC patients have more defects in homologous recombination repair (HRR) than patients with sporadic breast cancer." (PMID 33193564, 2020). "In total, the panel covered about 80% of all BRCA1/2, CHEK2, PALB2, NBN, and RECQL mutation detection in Polish high-risk families with breast cancer." (PMID 32824581, 2020). "This frameshift mutation resulted in a 40% cumulative risk of developing breast cancer by age 70 (95% CI, 17–77), similar to that for BRCA2 mutation carriers (~45%; 95% CI, 31–56), implying a striking role of PALB2 in predisposition to breast cancer." (PMID 32185139, 2020). "Partner and localizer of BRCA2 (PALB2) is essential to homologous recombination repair in response to double-stranded breaks in DNA4 and is a more recently identified breast cancer predisposing gene." (PMID 32300229, 2020). "In this article, authors found among 15 PALB2-germline mutant breast cancer patients, 10 were PALB2-NULL patients with both somatic and germline PALB2 mutations and 5 were PALB2-HET patients with only germline PALB2 mutations." (PMID 33193564, 2020). "The 10-year adjusted hazard ratio for all-cause mortality was 2.27 (95% CI, 1.64–3.15; p < 0.0001), indicating an adverse prognostic effect of PALB2 in breast cancer." (PMID 32185139, 2020). "Other breast cancer susceptibility genes have recessive phenotypes associated with biallelic PVs, including Fanconi Anemia for BRCA2 and PALB2, Ataxia Telangiectasia for ATM, and Nijmegen Breakage Syndrome for NBN." (PMID 31993860, 2020). "Abnormal expression of BRCA1, BRCA2, and PALB2 has been observed in about 10% of breast cancer cases." (PMID 32824813, 2020). "Meanwhile, numerous studies have associated mutations in moderate-penetrance genes, including PALB2, ATM, CHEK2, BRIP1, with increased breast cancer risk of two to four-fold compared to the 10% risk of the general population." (PMID 32091409, 2020). "To date, multiple breast cancer predisposition genes have been identified, mainly from studies of women of European ancestry, including BRCA1, BRCA2, PALB2, CHEK2, and ATM, which together accounted for 25% of the familial risk." (PMID 32318955, 2020). "In our previous study, twenty recurrent mutations were found in six breast-cancer-predisposing genes (BRCA1, BRCA2, CHEK2, PALB2, NBN, and RECQL) in Polish breast cancer patients." (PMID 32824581, 2020). "We genotyped 2464 women with breast cancer diagnosed below age 41 years for twenty recurrent germline mutations in six genes, including BRCA1, BRCA2 CHEK2, PALB2, NBN, and RECQL." (PMID 32824581, 2020). "All of the heterozygous germline PALB2 mutations that we detected in advanced breast cancers and familial breast cancers in the Geneplus cohort were high-risk LOF mutations, whereas all of the PALB2 somatic mutations were moderate-risk missense mutations." (PMID 33193564, 2020). "Several FA genes, such as BRCA1/FANCS, BRCA2/FANCD1, PALB2/FANCN, and RAD51C/FANCO have been confirmed to be breast carcinoma susceptibility genes at present." (PMID 32300589, 2020).